SNORA62 (small nucleolar RNA, H/ACA box 62)
Synonyms: E2; E2-1; RNE2; RNU108
Gene: Small nucleolar RNA gene on chromosome 3 (39,411,054 to 39,411,206, forward strand). Ensembl gene ENSG00000202363.
Gene Ontology:
Biological process: RNA processing
Cellular component: nucleolus
Homologues: Orthologues: chimpanzee SNORA62 (99% identical), macaque SNORA62 (99% identical), pig SNORA62 (93% identical), rabbit SNORA62 (90% identical), guinea pig SNORA62 (82% identical), mouse Snora62 (82% identical), rat Snora62 (82% identical). Paralogues in human: SNORA62 (84% identical), SNORA62 (80% identical), SNORA62 (76% identical), SNORA6 (71% identical), SNORA62 (54% identical), SNORA62 (41% identical).
Diseases named in the same sentence as SNORA62 in open-access papers:
SNORA62 is named in the same sentence as 1 disease in open-access papers, as found by Europe PMC text mining. Sharing a sentence is not in itself a finding about the gene and the disease. The quoted sentences say what the papers report.
infection (1 paper, 2025). The state of being infected such as from the introduction of a foreign agent such as serum, vaccine, antigenic substance or organism. "In contrast to expression changes induced by Delta infection, RT-qPCR validation of Omicron BA.2-infected cells only identified significant regulation of SNORA62, while expression of SNORA46, SNORD97, and SNORD109B was not significantly altered." (PMID 40510596, 2025).